STAT3 (signal transducer and activator of transcription 3)
Diseases named in the same sentence as STAT3 in open-access papers (continued):
Sharing a sentence is not in itself a finding about the gene and the disease.
tumor (continued). "Molecular docking analysis confirmed that API binds strongly to CDK1, and further experiments demonstrated that API suppresses NiNP-induced tumor growth both in laboratory cell models and in living organisms, while also blocking the activity of the CDK1/STAT3/FASN axis." (PMID 41226659, 2025). "STAT3 is also involved in CSC maintenance and CSC-mediated tumor metastasis." (PMID 39711287, 2025). "By activating downstream oncogenic signaling networks such as PI3K/AKT, MAPK/ERK, and STAT3, HER2 overexpression remodels the tumor microenvironment and induces epithelial-mesenchymal transition (EMT), thereby promoting tumor invasion, metastasis, and treatment resistance." (PMID 40438678, 2025). "Importantly, the combination inhibited tumor growth and reduced PD-L1 expression by targeting the EGFR/JAK/STAT3 signaling pathway, demonstrating potential to overcome anti-PD1 therapy resistance." (PMID 40347254, 2025). "Modulating key inflammatory mediators, including NF-κB, STAT3, and PI3K, may help reduce the tumor-promoting effects of neutrophils while preserving or amplifying their tumor-fighting functions." (PMID 40486614, 2025). "Current investigations suggest that STAT3 and NANOG may have important roles at multiple stages of tumour progression." (PMID 40729003, 2025). "It has been widely documented that IL-6 mediated activation of STAT3 signaling further triggers the transcription of various downstream target genes, including MMPs, Cyclin family members, and EMT makers, enhancing tumor cell survival, proliferation and invasion." (PMID 40055805, 2025). "Through activation of key pathways such as STAT3, NF-κB, and SMAD, these cytokines promote EMT, reprogram immune cell behavior (e.g., M2 macrophage polarization), and sustain transcriptional plasticity in tumor cells." (PMID 40933989, 2025). "An immunosuppressive tumor microenvironment is induced and cancer progression is deteriorated by abnormal stimulation of the Janus kinase 2/signal transducer and activator of transcription 3 (JAK2/STAT3) signaling pathway." (PMID 40149863, 2025). "In addition, sustained interferon signaling leads to the dominance of selectively activated M2 macrophages and myeloid-derived suppressor cells (MDSCs), resulting in immunosuppression and invasion of tumor cells in an IFN-λ-and STAT3-dependent manner." (PMID 41359111, 2025). "Mechanistically, it suppresses constitutive activation of nuclear factor kappa B (NF-κB) and Janus kinase/signal transducer and activator of transcription 3 (JAK/STAT3) signaling, thereby inhibiting tumor-promoting inflammation and enhancing apoptotic signaling." (PMID 41465187, 2025). "STAT3 activation in NK cells reduces their effectiveness by downregulating essential receptors such as NKG2D, NKp30, and DNAM-1, while also decreasing the production of perforin and granzyme B. This impairs their ability to kill tumor cells." (PMID 39859231, 2025). "Western blot analysis showed that KPC tumor-induced increase in the levels of total ubiquitinated proteins, MAFbx, MuRF1, ratio of LC3B-II/I, and p-STAT3 protein in skeletal muscle were significantly reduced in 4μ8C-treated mice compared to corresponding controls treated with vehicle alone." (PMID 40655023, 2025). "The study revealed that, as the tumor advanced, there was a significant increase in copy number variation (CNV) and the activity of tumor-related signaling pathways, such as TGF-β, Wnt, and STAT3, leading to enhanced proliferation and invasiveness of tumor cells." (PMID 40867511, 2025). "While neutrophils did not express STAT3 in our NStat3−/− mice, we observed strong overexpression of this molecule in macrophages (possibly as a compensatory mechanism), and yet tumor growth was impaired in such mice." (PMID 40885734, 2025). "In tumor sphere formation assay, the diameter of spheres in the GPM6B overexpression group was smaller than that in the control group, and the expression of β-catenin, p-STAT3, and c-Myc also reduced." (PMID 41450963, 2025).
tumor (continued). "In conclusion, our findings establish STAT3 inhibition via TTI-101 as a promising early therapeutic/preventative approach for KM-LUAD that can reduce tumor burden, reprogram the TIME, and enhance anti-tumor immunity." (PMID 40356899, 2025). "Furthermore, naringenin inhibits the PI3K/Akt/mTOR and IL-6/STAT3 signaling pathways, key oncogenic routes frequently exploited by BPA to drive tumor progression." (PMID 41440754, 2025). "Moreover, in the tumor microenvironment, activation of the JAK/STAT3 pathway by IL-6 occurs in both cancer cells and infiltrating immune cells, which can contribute to tumor progression." (PMID 40643463, 2025). "Moreover, in HPV-positive BC patients, tumor tissue exhibits higher levels of IL-6, IL-17, TNF-α, and TGF-β, along with activation of NF-κB and STAT3." (PMID 41597595, 2025). "Additionally, LCN2 binds to SLC22A17 on tumor cells themselves, activating JAK2/STAT3 and upregulating VEGF-A expression, thereby promoting tumor angiogenesis." (PMID 41436606, 2025). "Compounding this, platinum treatment may activate the STAT3 pathway by increasing IL-6, IL-10, and PGE2 production, leading to M2 polarization and tumor progression." (PMID 41280929, 2025). "The upregulation of the p50/p55 regulatory subunits of the PI3 kinase in tumor cells is a consequence of an increase in inflammatory cytokine signaling through the JAK/STAT pathway, in particular tyrosine-phosphorylated (i.e., activated) STAT3 (right)." (PMID 40624726, 2025). "Among them, CAFs can promote tumor proliferation, migration and drug resistance by activating PI3K/AKT, STAT3 and other pathways through secreting CXCL12, IL-6, etc., and form a pro-cancer positive feedback loop with immunosuppressive cells such as MDSC and TAM." (PMID 40860340, 2025). "This aligns with studies demonstrating that STAT3 activation (p-STAT3), not total STAT3 mRNA levels, drives tumor progression and poor survival, likely via cell-autonomous and immune-mediated mechanisms." (PMID 40636126, 2025). "However, treatment with the STAT3 inhibitor SH4-54, either alone or in combination with anakinra, significantly suppressed tumor growth in the BM." (PMID 41436606, 2025). "In these factors, like Interferon Regulatory Factor 1 (IRF1) and Nuclear factor, erythroid 2 like 2 (NFE2L2) have been reported to function in the anti-tumor capacity, while HIF-1 alpha (HIF1A) and Signal transducer and activator of transcription 3 (STAT3) to support tumor growth and immune evasion." (PMID 40230843, 2025). "Furthermore, acetate engaged G protein-coupled receptor 43 (GPR43) on hepatocytes, inhibiting the IL-6/JAK1/STAT3 pathway, inducing apoptosis of NAFLD/HCC tumor cells, preventing tumor formation, and enhancing intestinal barrier function." (PMID 40165786, 2025). "First, grade II-III TAM-MGs showed female enrichment of pathways related to anti-tumor inflammatory activity (IFN alpha response, IFN gamma response, and IL6 JAK STAT3 signaling), as well as pathways involved in lipid metabolism (adipogenesis and cholesterol homeostasis)." (PMID 38895459, 2025). "Further, LINC02268 could activate the interleukin-6 (IL6)/janus kinase (JAK)/signal transducer and activator of transcription 3 (STAT3) signaling pathway, crucial for driving tumor advancement and metastasis in the tumor microenvironment." (PMID 40538623, 2025). "Notably, SOX18 appears to function as a central node within a transcriptional network involving MEF2C, p-STAT3, and VCAM1—particularly in the tumor vasculature and invasive front—underscoring its relevance to tumor microenvironment remodeling." (PMID 41373817, 2025).
tumor (continued). "We observed that tumour cells activate the STAT3 and STAT1 signalling pathways, but not the PI3K–AKT or MAPK pathways, after the IL‐11 challenge." (PMID 40673604, 2025). "This pathway not only supports tumor growth despite CDK4/6 blockade but also contributes to a more aggressive and therapy-resistant phenotype, underscoring the therapeutic potential of dual inhibition strategies targeting both CDK4/6 and IL-6/STAT3 in TNBC." (PMID 41148817, 2025). "STAT3 is considered to be one of the hallmarks of GBM aggressiveness and contributes to tumor development and progression in several ways, such as inducing cell proliferation, inhibiting the apoptotic process, and promoting tumor cell migration and invasion." (PMID 39949739, 2025). "Additionally, strategies involving the IL-2 receptor β chain (IL-2Rβ) coupled with STAT3/5 signaling have been explored to improve CAR-NK cell persistence and anti-tumor efficacy." (PMID 38263004, 2024). "Additionally, STAT3 was found to increase the expression of S100A8/9 proteins, which promotes the clustering of MDSCs in the tumor microenvironment (TME)." (PMID 38717677, 2024). "A similar finding was observed in the LLC xenograft C57BL/6 N mouse model, which showed that treatment with βT3 reduced tumour size, reduced PD-L1 expression, as well as inhibition of JAK2/STAT3 pathway, increased CD8+ T-cell population and elevated granzyme B levels." (PMID 39416707, 2024). "Inhibition of STAT3 can downregulate HIF-1 and VEGF and inhibit tumor growth and angiogenesis." (PMID 39055895, 2024). "Furthermore, combined treatment with PQR309 and gemcitabine reduced p-STAT3, HSP60, p-GSK-3β protein levels in the xenograft tumor tissues, according to western blotting analysis." (PMID 38555280, 2024). "Three other studies have confirmed that miR-124 could inhibit the protein expression of STAT3 by directly targeting the 3′-UTR that binds STAT3, thereby suppress the invasive and migratory ability of tumor cells and help to overcome chemoresistance." (PMID 38420199, 2024). "It was shown that the upregulation of lncRNA ITIH4-AS1 leads to downregulation or depletion of RE1 silencing transcription factor (REST) in CRC, which consequently promotes ITIH4-AS1 expression and induces tumor proliferation and metastasis through JAK/STAT3 pathway." (PMID 39136000, 2024). "For instance, PD-L1 expression is induced in tumor cells by IFN-γ/STAT-1 and IL-6/STAT3 signaling." (PMID 39596207, 2024). "The role of STAT3 across a continuum of molecular processes, such as PDAC tumorigenesis and progression, immune escape, drug resistance and stemness, and modulation of the tumor microenvironment (TME), are only a tip of the iceberg." (PMID 38464736, 2024). "Frequent downregulation of SPOP in UBC cells resulted in STAT3 protein stabilization, thereby endowing UBC cells with CSC characteristics, which may represent an intrinsic driver of tumor aggressiveness." (PMID 39479456, 2024). "Indeed, MAPK, JAK/STAT3, and PI3K are only a few of the signalling pathways that are activated by IL-6, and these pathways support the formation of tumours, have anti-apoptotic properties, and preserve phenotypic tumour progenitor cells." (PMID 39554609, 2024). "Nevertheless, this cytokine, through the IL-10/STAT3 or TLR4/IL-10 signaling pathways, promotes the formation of M2 macrophages and activates the expression of the genes responsible for anti-apoptotic, pro-tumor and immunosuppressive activity." (PMID 39057050, 2024).
tumor (continued). "Signal transducer and activator of transcription 3 (STAT3) is frequently overactivated in various human cancers, serving as a crucial signaling node in tumor cells and the cellular components of the TME, especially in tumor-infiltrating immune cells." (PMID 38650924, 2024). "STAT3 activated LCN2 secreted by neutrophils could also contribute to EMT, invasion and migration of tumour cells." (PMID 39021279, 2024). "In exploring tumor cell signatures linked to ICI response, non-responder attributes were regulated by STAT3 and NFKB1." (PMID 39514276, 2024). "Importantly, the translocation of signal transducer and activator of transcription 3 (STAT3) requires RAN to subsequently stimulate cellular differentiation, proliferation, and tumor cell invasion." (PMID 39041645, 2024). "However, in tumor cells, 50%–90% of tumor cells exhibit sustained activation and in 66%–83% of GBM, the STAT3 pathway is constitutively activated." (PMID 39563863, 2024). "Moreover, it has been shown that S1PR1 is intimately related to the ongoing activation of signal transducer and activator of transcription-3 (STAT3) and the expression of IL-6 in both tumor cells and the surrounding tissues." (PMID 38933330, 2024). "SCAMs can also promote tumor epithelial cell proliferation and tumor growth in an immunosuppressive non-dependent manner by secreting the ligand oncostatin-M (OSM), which induces JAK/STAT3 signaling." (PMID 38725629, 2024). "Additionally, other researchers highlighted STAT3 as a critical regulator in CCA, influencing angiogenesis, immunosuppression, and tumor invasion 37,38." (PMID 38370386, 2024). "However, STAT3 and STAT6 are often over-activated in tumor cells to induce tumor invasion and immune suppression." (PMID 39525474, 2024). "Furthermore, western blot and qRT-PCR assays revealed that FAK inhibitor PF573228 efficiently down-regulated p-STAT3 and IL-4 levels and the STAT3 inhibitor Stattic inhibited the POSTN-induced IL-4 upregulation in tumor cells." (PMID 38773979, 2024). "Together, we have delineated the tumor-suppressive function of SPOP in UBC, demonstrating that it restricts bladder CSC characteristics and TAM recruitment and polarization by targeting the STAT3 oncoprotein for degradation." (PMID 39479456, 2024). "While previous studies have shown that WNT7A promotes tumor progression through the Wnt-β-catenin pathway, our study found that it activates a previously undescribed STAT3-mediated noncanonical Wnt pathway in HNSCC." (PMID 38246919, 2024). "In addition, SIX4, STAT3, IL-6, SOX2, and C-JUN were upregulated in tumor spheres compared to adherent cells." (PMID 39309424, 2024). "Similarly, in tumor cell implantation (TCI) models, the upregulated levels of microglial p-JAK2 and p-STAT3 proteins in the spinal cord horn are involved in the development and maintenance of cancer-induced bone pain (CIBP)." (PMID 37307838, 2024). "The development of tumor progression by M2-TAM involves a complex interaction of signals, including stroma cells through cytokines, and chemokines, which stimulates the crosstalk of the STAT-3 pathway with NF-κB." (PMID 39061137, 2024). "Continuous stimulation of the pro-inflammatory pathways, especially the signal transducer and activator of transcription 3 (STAT3)- and NF-kB-dependent cascades, maintains a prototypic inflamed tumor microenvironment, independently driving the initial steps that lead to oncogenesis." (PMID 39409925, 2024). "Additionally, IL-6 activates the STAT3 signaling cascade, leading to increased VEGF expression, which promotes tumor angiogenesis and growth." (PMID 37713112, 2024). "However, it was reported that αToc upregulates the expression of PD-L1 and activates the PD-L1/PD-1 axis via JAK/STAT3 and ERK pathways, resulting in tumour growth in the LLC xenograft mice." (PMID 39416707, 2024). "As a critical regulator of the GP130/IL-6/STAT3 pathway, CD109 may act as a crucial link between chronic inflammation and tumor development." (PMID 39990858, 2024).
tumor (continued). "Notably, we observed JAK1, JAK2, STAT3 were all located in ATC tumor cells, suggesting a crucial role of JAK1/2-STAT3 activation in maintaining malignant features of ATC tumor cells." (PMID 38336839, 2024). "Our study found that The STAT family proteins, particularly STAT3 and STAT5, are well-known for their vital contributions to various aspects of tumor progression, including cell proliferation 34, apoptosis resistance 35, promotion of carcinoma stemness, and development of drug resistance." (PMID 38495496, 2024). "Moreover, the IHC staining also confirmed that METTL3, p-JAK2/p-STAT3, GLUT1, and Ki67 were significantly elevated in the mice tumor with injection of MHCC97H mixed with Exo-incubated macrophages or M2 macrophages." (PMID 39247822, 2024). "Compelling evidence suggests that IL-6 derived from CAFs mediates therapeutic resistance, including chemoresistance by upregulating CXCR7 expression via STAT3/NF-κb pathway in ESCC, and IL-6 blockade improves checkpoint blockade therapy and promotes tumor immunity." (PMID 39334513, 2024). "mDA cells exposed to the tumor microenvironment induced abnormal proliferation in vitro and in vivo, which was ascribed to the hyperactivation of proliferation‐related genes, the JAK/STAT3 pathway, and cytokine stimulation." (PMID 39563017, 2024). "It was also the case of STAT3 whose expression consistently increased in original tumor samples but not in derived primocultures or matched cryopreserved tumor specimens." (PMID 38654280, 2024). "In xenograft tumors, querying GH downstream intracellular signaling intermediates predicted from PDAC patient tumor analysis show that GHRA-treated groups have significant and consistent reductions in the phosphorylation states of STAT5, STAT3, as well as SRC and AKT in both male and female mice." (PMID 39000545, 2024). "Furthermore, methylation of STAT3 at arginine 609 by PRMT5 is important for its transcriptional activity and support of tumour growth and CSC maintenance." (PMID 38760429, 2024). "The STAT3 pathway, mediated by ATP6V0D1, consistently enhances alkaliptosis in tumor cells." (PMID 39439891, 2024). "It has been found that the activation of STAT3 can regulate the downstream target gene c-Myc and thus activate the STAT3/c-Myc signaling pathway, which interacts with the mTOR/PKM2 signaling pathway in GC cells to regulate the glycolysis and acidic microenvironment in tumor cells." (PMID 39816354, 2024). "Enhanced activity of the STAT3 transcription factors and overactivation of intracellular signaling cascades involving the MAPK and PI3K-Akt pathways, all contribute to elevated PD-L1 expression on the cell membranes of malignant tumor cells." (PMID 38541123, 2024). "The inhibitor significantly reduced tumor radioactivity accumulation and the tumor-to-blood ratio in the xenografted mice after [18F]FBNAF administration, suggesting the specific binding of [18F]FBNAF to STAT3 in tumor tissues." (PMID 38834900, 2024). "Deletion of myeloid‐specific METTL3, which is the catalytic component of methyltransferase complex, reduces the translation of SPRED2 which ultimately increases the activation of STAT3 and NF‐kB via the ERK pathway promoting increased tumor growth and metastasis." (PMID 38703051, 2024). "Furthermore, GSEV result spot that tumor promotive signal such KRAS, EMT and IL-6/JAK/STAT3 are restricted under anoikis-related condition." (PMID 39568815, 2024). "Moreover, it was observed that RA attenuated tumor growth by decreasing the expression of anti-apoptotic factors by the inhibition of TLR4-mediated NF-kB and signal transducer and activator of transcription 3 (STAT3)." (PMID 39519255, 2024). "During the late stages of CAC development, tumor-derived sIL-6R rather than membrane-bound IL-6R induces STAT3 activation and accelerates tumor growth." (PMID 38182653, 2024).